KEAP1 (kelch like ECH associated protein 1)
Diseases named in the same sentence as KEAP1 in open-access papers (continued):
Sharing a sentence is not in itself a finding about the gene and the disease.
lung adenocarcinoma (continued). "More than 400 drugs and compounds were tested on KEAP1/NFE2L2-mutant and wild-type lung adenocarcinoma cell lines in GDSC." (PMID 35371318, 2022). "Coexisting alterations in KEAP1 and STK11 among other genes define a subset of lung adenocarcinoma unresponsive to immunotherapy." (PMID 33889302, 2021). "In lung adenocarcinoma, STK11/KEAP1 commutation leads to resistance to pharmacologically induced ferroptosis and high expression of ferroptosis-protective genes, which is associated with early death and aggressive tumor development." (PMID 35047016, 2021). "Generally, our study comprehensively analyzed the multiplatform data of TCGA to compare the biologic characteristics, intrinsic heterogeneities, and clinical features of the KEAP1/NFE2L2/CUL3 mutant and wild lung adenocarcinoma patients." (PMID 34617407, 2021). "Mutations in the KEAP1 or NFE2L2 genes are mutually exclusive and occur in NSCLC patients with a variable incidence (3.5–15% for KEAP1; 12–17% for NFE2L2), with the first ones mainly clustered with the lung adenocarcinoma (LUAD) histology." (PMID 32971994, 2020). "(a) CDO1 mRNA expression of normal lung (Normal) or or KEAP1 wild-type (WT) and mutant (MUT) lung adenocarcinoma patient tumor samples." (PMID 31107239, 2019). "(b) Methylation of the CDO1 promoter in samples from normal lung (Normal) or KEAP1 wild-type (WT) and mutant (MUT) lung adenocarcinoma patient tumor samples." (PMID 31107239, 2019). "The KEAP1/NRF2 pathway is genetically altered in approximately 30% of lung squamous cell carcinomas and approximately 20% of lung adenocarcinomas." (PMID 28145866, 2017). "Gene mutations observed differ between lung adenocarcinoma and lung squamous cell carcinoma, with KRAS, EGFR, LPHN3, KEAP1, and TLR4 being relatively common in lung adenocarcinoma, whereas BAI3, FBXW7, GRM8, ERBB4, MUC16, and RUNX1T1 are common in lung squamous cell carcinoma." (PMID 39594843, 2024). "Moreover, the genomic alterations of KEAP1 and NFE2L2 were reported to play crucial roles in lung adenocarcinoma 13-15." (PMID 35371318, 2022). "Another study investigated the prognostic value of STK11/KEAP1 mutations in an observational real-world lung adenocarcinoma cohort, and the results suggested that STK11/KEAP1 mutations are prognostic, not predictive biomarkers for immunotherapy." (PMID 35945957, 2022). "Immunohistochemistry was conducted to compare Keap1 expression in lung adenocarcinoma tissues and matched non-cancerous tissues, and the correlation between Keap1 expression and clinicopathological features was analyzed." (PMID 34466284, 2021). "Indeed, we found that although in the TCGA lung adenocarcinoma data, the cumulative alteration frequency of NRF2, KEAP1, and CUL3 is 23%, 58% of patients within our lung adenocarcinoma cohort had high levels of NRF2 protein." (PMID 31455821, 2019). "The two most common non-oncogene-driven mutations in lung adenocarcinoma, STK11 (serine/threonine kinase 11) and KEAP1 (Kelch-like ECH-associated protein 1) mutations, were found to be predictors of poor outcomes in patients with NSCLC treated with immunotherapy." (PMID 40650126, 2025). "In this regard, the group of Heymach took advantage of isogenic pairs of murine and human KRAS-driven lung adenocarcinoma cells (K tumors) with concomitant knockdown of LKB1 (KL tumors) and KEAP1 (KLK tumors) to explore the potential metabolic adaptations that might be targeted." (PMID 32443774, 2020). "However, the expression of Nrf2 and Keap1 in lung adenocarcinoma patients with different "driver gene" is not clear." (PMID 29587953, 2018).
lung adenocarcinoma (continued). "Although the present study did not assess the KEAP1 and/or STK11 gene alterations and the detailed types of adenocarcinomas, above‐mentioned reports might partially explain why TTF‐1 negative lung adenocarcinoma showed worse outcomes with ICI monotherapy in our study." (PMID 35808895, 2022).
non-small cell lung carcinoma (102 papers, 2012 to 2026). A group of at least three distinct histological types of lung cancer, including non-small cell squamous cell carcinoma, adenocarcinoma, and large cell carcinoma. "One central resistance mechanism involves the activation of NRF2, a transcription factor stabilized by mutations in KEAP1—mutations that are particularly common in non-small cell lung cancer." (PMID 40733290, 2025). "KEAP1, a tumor suppressor gene that promotes antitumor immunity, is frequently mutated in non-small cell lung cancer, leading to increased NRF2 activity and poorer clinical outcomes." (PMID 40565184, 2025). "In particular, in Kelch-like ECH-associated protein 1 (KEAP1) mutant non-small cell lung cancer (NSCLC), the overexpression of FSP1 induced cross-resistance to GPX4 inhibitors." (PMID 40559667, 2025). "KEAP1 mutations are observed in 11% to 27% of advanced non-small-cell lung cancer, suggesting its role as a tumor suppressor." (PMID 40190348, 2025). "KEAP1 mutations have been associated with poor prognosis in non-small-cell lung cancer, further underscoring the need to better understand KEAP1 functions beyond NRF2 regulation." (PMID 39941813, 2025). "While KEAP1 mutations have been widely reported and studied in malignancies such as non-small cell lung cancer, their presence and role in thyroid cancer have been largely overlooked." (PMID 41573641, 2025). "Loss-of-function (LOF) mutations in the repressor protein KEAP1 are common in non-small cell lung cancer, particularly adenocarcinoma." (PMID 38184997, 2024). "The loss-of-function mutations in KEAP1 confer radiation resistance in non-small cell lung cancer (NSCLC)." (PMID 37251921, 2023). "The existence of KEAP1 or NRF2 mutations in patients with non-small cell lung cancer was correlated with poor responses to chemotherapy, suggesting that NRF2 activation causes resistance to therapeutic intervention." (PMID 35053572, 2022). "KEAP1- or NRF2-mutation-based constitutive activations have been reported in non-small cell lung cancer and esophageal cancer." (PMID 35053572, 2022). "The KEAP1/NRF2 genes are highly mutated in non-small cell lung cancer (NSCLC) and tend to be found in heavy smokers." (PMID 35911967, 2022). "The KEAP1-NFE2L2 (Kelch-like ECH-associated protein 1 (KEAP1)-Nuclear factor (erythroid-derived 2)-like 2 (NFE2L2)) mutations are associated with resistance to chemotherapy or immunotherapy in non-small cell lung cancer (NSCLC)." (PMID 34381706, 2021). "Mutations in ARID1A are frequent in non-small cell lung cancer, colon cancer, bladder cancer and breast cancer, whereas mutations in KEAP1 and STK11 was predominate in non-small cell lung cancer (8.62% and 11.75%, respectively)." (PMID 34302033, 2021). "A loss of function mutation of Keap1 is frequently associated with drug-resistant non-small cell lung cancer." (PMID 34316328, 2021). "Cancer genome sequencing studies have identified frequent gain of function mutations in the KEAP1/NRF2 pathway in human non-small cell lung carcinoma (NSCLC)." (PMID 34566633, 2021). "Low expression or inactivated mutation of Keap1 occurs in human non-small-cell lung carcinoma tissues including adenocarcinoma, leading to the increased expression and activation of Nrf2." (PMID 34205320, 2021). "Mutations in the KEAP1 (Kelch-like ECH-associated Protein-1) gene are common abnormalities in non-small cell lung cancer (NSCLC), gallbladder, liver, ovarian, endometrial, and lung papillary cancers." (PMID 29988316, 2018).
non-small cell lung carcinoma (continued). "We found that platinum-based therapies modified the NRF2 signaling pathway differently in KEAP1-mutated non-small cell lung cancer (NSCLC) cell lines compared with wild-type KEAP1 cell lines." (PMID 27601007, 2016). "The Keap1 gene mutation has been previously identified in 3–5% of non-small cell lung cancer (NSCLC) cases, however, the correlation between the mutation status and clinicopathological features was not well defined." (PMID 24137397, 2013). "Experimental studies indicate that the deletion of KEAP1 results in tumor aggressiveness and resistance to radiotherapy, with KEAP1 mutations in non-small cell lung cancer (NSCLC) was identified as associated with an increased risk of local recurrence after radiation therapy." (PMID 40272602, 2025). "For this effect to take place, it is necessary for cysteine dioxygenase 1 (CDO1), an enzyme that catalyzes the irreversible conversion of cysteine to cysteine sulfinic acid, to be silenced, as it happens in human non-small-cell lung cancers that harbor mutations in KEAP1." (PMID 36509429, 2023). "If MTX-211 promotes NRF2 degradation through Keap1, it may hinder the therapeutic application in Keap1-mutated cancers, such as non-small cell lung cancer." (PMID 37108769, 2023). "Singh and colleagues used KEAP1-mutated non-small-cell lung cancer (NSCLC) cell lines stably carrying ARE luciferase reporter gene fragment as screening platforms and identified ML385 as a potent NRF2 inhibitor that directly binds to NRF2 then interrupts the binding of NRF2–MAFG complex to ARE." (PMID 33915987, 2021). "Notably, CDO1 is preferentially silenced by promoter methylation in human non-small cell lung cancers (NSCLC) harboring mutations in KEAP1, the negative regulator of NRF2." (PMID 31107239, 2019). "Loss of liver kinase B1 (LKB1, also known as serine/threonine kinase 11 or STK11) in non-small cell lung cancer (NSCLC) has been shown to enrich these tumors with KEAP1 mutations, making these cancers vulnerable to inhibition of NRF2-mediated antioxidant response." (PMID 31288436, 2019). "Additionally, we also examined the effect of WDR23 overexpression in H460 human non-small-cell lung carcinoma cells, which also harbor a KEAP1 mutation (different from that of A549) that results in nuclear NRF2." (PMID 28453520, 2017). "Evidence that repression of NRF2 by KEAP1 is impaired in human cancer came initially from the laboratory of Shyam Biswal through the demonstration that the KEAP1 gene is subject to somatic mutations in some cell lines and clinical samples from patients with non-small cell lung cancer (NSCLC)." (PMID 33276631, 2020). "Our findings suggest that YTHDF1 does not enhance prostate cancer progression through the m6A-modified KEAP1 and Nrf2 axis, as observed in non-small cell lung cancer, highlighting its context-dependent function across different cancer types." (PMID 40251202, 2025). "Emerging trials combining PI3K/mTOR inhibitors or glutaminase blockers (CB-839) with conventional chemotherapy in KEAP1-mutant non-small-cell lung cancer exemplify how mechanistic insights are being translated into clinical strategies." (PMID 41470226, 2025). "The orphan nuclear receptor NR0B1 is a recently identified NRF2 target that has been shown to support the anchorage-independent growth of KEAP1-mutant non-small cell lung cancer (NSCLC) cells." (PMID 40864301, 2025). "For instance, dual inhibition of FSP1 and NRF2 can sensitize KEAP1-mutant non-small cell lung cancers to ferroptosis-induced cell death." (PMID 40733290, 2025). "In non-small cell lung cancer, Nestin interacts with the Kelch domain of Keap1, leading to the escape of Nrf2 from Keap1-mediated degradation and subsequent promotion of antioxidant enzymes." (PMID 39354366, 2024). "This suggests that the Nestin–Keap1–Nrf2 axis functions as a regulator of cellular redox homeostasis and confers resistance to oxidative stress in non-small cell lung cancer." (PMID 39354366, 2024).
non-small cell lung carcinoma (continued). "Knockout of SLC27A5 activates the KEAP1/NRF2 pathway, which is linked to chemoresistance in non-small cell lung cancer patients and different types of cancer cell lines." (PMID 38797968, 2024). "Point mutations in the central intervening region (IVR) or in the Kelch domain of KEAP1 that alter its interaction with NRF2 have been reported in non-small cell lung cancer cells (NSCLC)." (PMID 37660919, 2023). "KEAP1/NFE2L2/CUL3 represented a mechanism of resistance to tyrosine kinase inhibitor in patients with EGFR-mutant non-small cell lung cancer." (PMID 35371318, 2022). "Almost 40% of LCNECs have molecular alterations often identified in non-small cell lung cancer (STK11, and KEAP1 mutations) with high expression of ASCL1 and neuroendocrine markers (defined as type I LCNEC)." (PMID 36553576, 2022). "The Kelch-like ECH-associated protein 1 (KEAP1) and the nuclear factor erythroid-2-related factor 2 (NFE2L2) mutations were found in more than 20% patients with non-small cell lung cancer, which represented one of the most important genomic subtypes 11,12." (PMID 35371318, 2022). "Non-small-cell lung cancer (NSCLC) accounts for 80–85% of all diagnosed lung cancer cases, of which a third have mutations in the NRF2/KEAP1 circuit." (PMID 35667246, 2022). "Somatic mutations in SMARCA4 and/or BRG1 (Brahma-related gene 1) loss are present in a subset of non-small cell lung carcinomas with distinct morphological features, harboring less EGFR mutations, but more KRAS, STK11, and KEAP1 mutations." (PMID 36371186, 2022). "Inactivating mutations in Keap1 have been reported to induce several cancers, including breast cancer and non-small cell lung carcinoma (NSCLC), as well as squamous cell lung carcinomas (SCLCs), further actuating the tumorigenicity and resistance to chemotherapy." (PMID 33466626, 2021). "Scientific evidence about the presence of genetic and epigenetic abnormalities of the KEAP1 gene was firstly reported in non-small-cell lung cancer (NSCLC) and then described in other tumors." (PMID 32971994, 2020). "used next-generation sequencing (NGS) to analyze the tumor tissue of 1,391 patients with non-small cell lung carcinoma (NSCLC) and found that Keap1 mutations occurred in 11.3% (n = 157) and NRF2 mutations occurred in 3.5% (n = 49) of NSCLC patients." (PMID 33324555, 2020). "Specifically, we carried out individual and combinatorial microarray analysis of KEAP1 overexpression and NRF2 siRNA-knockdown in a KEAP1 mutant-A549 non-small cell lung cancer (NSCLC) cell line." (PMID 29050246, 2017). "Non-small cell lung cancer is the tumour type in which KEAP1/NRF2 dysfunction has most frequently been reported." (PMID 27824809, 2016). "The physiological relevance of the stoichiometric imbalance of Keap1 and Nrf2 is well illustrated in non-small cell lung cancer (NSCLC)." (PMID 24681086, 2014). "Additionally, elevated Nrf2 expression is associated with poor prognosis in non-small cell lung cancer (NSCLC), and the activation status of Nrf2 in KEAP1-mutant lung cancer patients serves as a predictor of tumor sensitivity to antioxidant therapies." (PMID 40563367, 2025). "Notably, the co-occurrence of KRAS and KEAP1 mutations has been linked to poorer clinical outcomes and reduced therapeutic efficacy in non-small cell lung cancer, further supporting a potential cooperative role of KEAP1 alterations and MAPK activation." (PMID 41573641, 2025). "FSP1 led to the resistance of non-small cell lung carcinoma cells (a KEAP1 mutant) to ferroptosis." (PMID 40002690, 2025). "Studies on non-small cell lung cancer (NSCLC), both preclinical and clinical, have demonstrated tight relationships among the resistance to chemotherapy, radiation therapy, and other agents, and the loss of function of Keap1 and overexpression of Nrf2." (PMID 39557840, 2024).